PINK1 (PTEN induced kinase 1)
Diseases named in the same sentence as PINK1 in open-access papers (continued):
Sharing a sentence is not in itself a finding about the gene and the disease.
retinal degeneration (4 papers, 2016 to 2024). Degeneration of the retina. "Further, the PINK1/Parkin-dependent mitochondrial quality control pathway alleviated the retinal degeneration associated with the TrpP365 mutation." (PMID 27054334, 2016). "In the TrpP365 retinal degeneration model, autophagy suppressed cellular calcium neurotoxicity, and this effect depended on the PINK1/Parkin pathway." (PMID 27054334, 2016). "Consistent with the PINK1 and Parkin results, the severity of retinal degeneration was alleviated by Drp1 overexpression and enhanced by Opa1 overexpression in 5-day-old TrpP365 flies." (PMID 27054334, 2016). "In addition, the retinal degeneration process was also suppressed by the coexpression of PINK1 and Parkin." (PMID 27054334, 2016). "The different effects of PINK1S346A and PINK1S346D on retinal degeneration are not due to expressing different levels of PINK1." (PMID 27906179, 2016). "Coexpression of TOM20-PINK1 and ParkinS94A did not result in a severe retinal degeneration phenotype as with wild-type Parkin, which suggested that PINK1 kinase activity toward Parkin is also essential for the activation of the PINK1/Parkin pathway." (PMID 27906179, 2016). "Unlike wild-type PINK1, coexpression of TOM20-PINK1S346A-GFP and Flag-Parkin did not lead to external retinal degeneration on the first day." (PMID 27906179, 2016).
tauopathies (4 papers, 2016 to 2025). "While much less is known about mutations in mitochondria-related genes in primary tauopathies, this research could be used towards developing an in vitro model by inducing mutations in the PINK1/Parkin/DJ-1/FBX07 genes in cell lines, such as the Lund human mesencephalic (LUHMES) cells." (PMID 39721496, 2025).
ulcerative colitis (4 papers, 2022 to 2025). An inflammatory bowel disease involving the mucosal surface of the large intestine and rectum. "In our study, we have focused on elucidating the roles of Activating Transcription Factor 7 (ATF7) and PTEN‐induced kinase 1 (PINK1) within the context of ulcerative colitis (UC) and its manifestation in intestinal epithelial cells (IECs)." (PMID 40586859, 2025). "However, the contribution of PINK1–Parkin–driven mitophagy to intestinal epithelial homeostasis, particularly during inflammation‐induced epithelial injury in ulcerative colitis, remains incompletely understood." (PMID 40903840, 2025). "Ulcerative colitis is associated with diminished ATF7 expression in intestinal epithelial cells, which compromises PINK1 transcriptional activation and leads to impaired mitophagy, mitochondrial dysfunction, and excessive reactive oxygen species (ROS) accumulation." (PMID 40586859, 2025).
adrenocortical tumors (3 papers, 2011 to 2021). "The combination of BUB1B, DLGAP5, and PINK1 can serve as a predictor of a poor outcome in adrenocortical tumors." (PMID 35095717, 2021). "Combined expression of BUB1B and PINK1 was the best predictor of overall survival in adrenocortical tumors by microarray." (PMID 22022424, 2011).
Atrophy (3 papers, 2018 to 2026). Any weakening or degeneration, especially through lack of use. "Cortical atrophy and frontal-executive dysfunction are also observed in heterozygous carriers that have only partial loss of PINK1, implicating PINK1 in an important neuroprotective role." (PMID 30783609, 2018). "In the full cohort, normative expression of MAPT, PINK1, and PSEN2 predicted regional atrophy after correction for spatial autocorrelation, although none survived multiple-testing correction." (PMID 41991538, 2026).
Cachexia (3 papers, 2022 to 2024). Severe weight loss, wasting of muscle, loss of appetite, and general debility related to a chronic disease. "Interestingly, clinical evidence indicates that the expressions of autophagic markers, including LC3B and PINK1 mRNA levels, were modulated among cancer patients with anorexia and cachexia." (PMID 39519555, 2024). "Our data showed that both in vitro cachexia models and HMGB1 treatment reduced autophagy and the expression of mitophagy-related proteins such as PINK1 and Parkin." (PMID 39000167, 2024). "The expression levels of mitophagy-related proteins, such as microtubule-associated protein 1 light chain 3 beta (MAP1LC3β), Parkin, PTEN induced kinase 1 (PINK1), and BCL2 interacting protein 3 (BNIP3), are altered in cachexia." (PMID 36361713, 2022).
diffuse large B-cell lymphoma (3 papers, 2020 to 2025). "In contrast, only Compagno reported that overexpression of PINK1 was found in diffuse large B cell lymphoma compared with normal tissues, with a P = 1.63E-17 and a fold change = 2.109." (PMID 33244455, 2020).
endometrial cancer (3 papers, 2021 to 2023). Primary or metastatic malignant neoplasm involving the endometrium (mucous membrane that lines the endometrial cavity). "Beyond the brain, it is worth noting that PINK1 protein expression can also be upregulated in breast, colorectal, and endometrial cancer tissues, whereas PINK1 inhibition restricts cancer cell proliferation." (PMID 34795558, 2021). "PINK1’s function seems to be not restricted to the brain, as PINK1 is also upregulated in breast, colorectal, and endometrial cancer tissues, whereas PINK1 inhibition reduces cancer cell proliferation." (PMID 35874823, 2022).
endothelial dysfunction (3 papers, 2018 to 2024). In vascular diseases, endothelial dysfunction is a systemic pathological state of the endothelium (the inner lining of blood vessels) and can be broadly defined as an imbalance between vasodilating and vasoconstricting substances produced by (or acting on) the endothelium. "Spermidine, a natural polyamine, stimulates mitophagy by the PINK1–parkin pathway and counters age-associated endothelial dysfunction." (PMID 39337408, 2024). "Taken together, these results demonstrate that Pink1/Parkin-mediated mitophagy is essential for MSCs to protect HUVECs against HG-induced apoptosis and endothelial dysfunction." (PMID 30082798, 2018). "Therefore, the purpose of this study was to determine the effect of enhancing PINK1–parkin-mediated removal of damaged mitochondria with spermidine on endothelial dysfunction in SLE." (PMID 39337408, 2024).
head and neck squamous cell carcinoma (3 papers, 2020 to 2026). A squamous cell carcinoma that arises from any of the following anatomic sites: lip and oral cavity, nasal cavity, paranasal sinuses, pharynx, larynx, and salivary glands. "For HNSC (head and neck squamous cell carcinoma), PINK1 was identified as a protective prognostic factor (OS: log rank P = 0.0072)." (PMID 33244455, 2020).
lupus (3 papers, 2021 to 2024). "We demonstrated that spermidine, which targets PINK1–parkin-mediated mitophagy, has beneficial effects on lupus mice: (a) improved endothelial function; (b) decreased inflammation; (c) enhanced mitophagy; and (d) did not decrease lupus disease activity." (PMID 39337408, 2024).
lymphoma (3 papers, 2020 to 2025). A malignant (clonal) proliferation of B- lymphocytes or T- lymphocytes which involves the lymph nodes, bone marrow and/or extranodal sites. "Additionally, the only PINK1 carrier in the PPMI study had a history of lymphoma and thyroid cancer." (PMID 41300754, 2025). "However, the mRNA expression of PINK1 was significantly upregulated in lymphoma." (PMID 33244455, 2020).
lysosomal storage disorder (3 papers, 2008 to 2023). "We also report here a novel phenotype in the surviving neurons of PINK1 deficient neurons which resembles the pathology observed in lysosomal storage diseases." (PMID 18560593, 2008).
MELAS (3 papers, 2017 to 2025). "It is worth noting that the levels of PINK1 and BNIP3L were decreased in the muscle of m.3243 A > G MELAS patients compared with the control group, indicating inhibition of mitochondrial autophagy initiation in MELAS." (PMID 38741129, 2024). "Apart from many targets including PINK1, FOXO1, PPARγ and Apaf-1 investigated before, MKNK2, GREM1 and EEF1A1 that might be potential targets of miR-27b-3p were revealed in the regulatory network of MELAS pathogenesis." (PMID 28139706, 2017).
metabolic syndrome (3 papers, 2015 to 2025). A cluster of metabolic risk factors for CARDIOVASCULAR DISEASES and TYPE 2 DIABETES MELLITUS. "Interestingly, supplementation of culture media with Spirulina platensis resulted in almost complete reversal of the impact of metabolic syndrome on PINK1 and Parkin genes." (PMID 28771165, 2017). "PINK1—Parkin mediated mitophagy protects endothelial cells from metabolic stress-induced mitochondrial damage and cell death, hence may provide a novel target for the development of therapeutic strategies in metabolic syndrome." (PMID 26161534, 2015). "Moreover, mitophagy, via PINK1/Parkin or BNIP3-dependent pathways, maintains mitochondrial integrity and restrains inflammation; impaired mitophagy, particularly in the context of metabolic syndrome, may blunt the efficacy of conditioning." (PMID 40885749, 2025).
Neurodegeneration (3 papers, 2009 to 2021). Progressive loss of neural cells and tissue. "Given the impact of mitochondrial dysfunction on neurodegeneration disorders we sought to rescue the Pink1 or park KD-mediated deleterious effects." (PMID 34218254, 2021).
nonalcoholic steatohepatitis (3 papers, 2022 to 2025). "Circ608 can promote PINK1-mediated mitophagy of HSCs by acting as a sponge of miR222 in non-alcoholic steatohepatitis (NASH)-related liver fibrosis." (PMID 35741077, 2022).
parkinsonian-pyramidal syndrome (3 papers, 2019 to 2025). A Parkinson's disease that has material basis in mutation in the FBXO7 gene on chromosome 22q12.3. "The interaction with Parkin and PINK1 has been suggested to be critical to the observed Parkinsonian pyramidal syndrome with a defect in mitophagy resulting in dopaminergic neuronal cell death." (PMID 30840666, 2019).
prediabetes (3 papers, 2017 to 2025). "Our study is the first report to demonstrate that MFN2, NIX, PINK1, and PARKIN expression was increased in subjects with prediabetes as compared to the healthy controls." (PMID 29326655, 2017). "In subjects with prediabetes, MFN2 (r = 0.558; p < 0.01), PINK1 (r = 0.534; p < 0.01), NIX (r = 0.637; p < 0.01) and LC3-II (r = 0.667; p < 0.01) mRNA expression was significantly and positively correlated with the HbA1C levels." (PMID 29326655, 2017). "PINK1 and NIX mRNA expression were significantly augmented by ~3- to 4-folds in subjects with prediabetes as compared to the controls (p < 0.05)." (PMID 29326655, 2017). "Nevertheless, one clinical study that focused on peripheral blood mononuclear cells reported that initial elevations of PARKIN/PINK1 and NIX mitophagy markers in prediabetes patients eventually decreased across newly diagnosed and advanced duration T2D patients." (PMID 38338783, 2024).
proteinopathy (3 papers, 2018 to 2023). "There is no chemical subtype that can accurately mimic a genetic mutation, and so we generated a new image-based genetic classifier to distinguish between the control, SNCA ×3 mutant (proteinopathy) and PINK1 mutant (mitochondriopathy) pathways." (PMID 37615030, 2023). "In this study, we reveal that Parkin and PINK1 are differentially misregulated in TDP-43 proteinopathy at RNA and protein levels." (PMID 30237395, 2018). "Upregulation of PRKN expression or RNAi-mediated downregulation of PINK1 levels suppressed TDP43-induced degenerative phenotype in Drosophila, indicating that PRKN and PINK1 are important components of TDP43-induced proteinopathy." (PMID 32582692, 2020). "In this study, we show that the increase of cleaved PINK1 reduces the reserve respiration capacity of mitochondria, which may contribute to disease progression in TDP-43 proteinopathy." (PMID 30237395, 2018).
thyroid cancer (3 papers, 2020 to 2025). "For THCA (thyroid carcinoma), PINK1 significantly affected overall survival but not relapse-free survival (OS: log-rank P = 0.041)." (PMID 33244455, 2020).
Tremor (3 papers, 2011 to 2023). An unintentional, oscillating to-and-fro muscle movement about a joint axis. "For instance, a PD patient with an SNCA pathogenic variant exhibited dorsal pain as a primary symptom, while another patient with the Leu347Pro PTEN-induced putative protein kinase 1 (PINK1) pathogenic variant developed long-term right-sided pain following right-hand tremor onset." (PMID 38020640, 2023).
Ureteral obstruction (3 papers, 2023 to 2024). Obstruction of the flow of urine through the ureter. "A study using an unilateral ureteral obstruction model demonstrated that loss of PINK1 accelerated renal extracellular matrix accumulation and kidney fibrosis." (PMID 37183600, 2023). "The results obtained showed significant decrease in the gene expression and protein levels of the mitophagy kinase PINK1 5 days after ureteral obstruction, which was partially prevented by JQ1." (PMID 37237996, 2023). "In experimental models, such as unilateral ureteral obstruction (UUO) mice, the deletion of phosphatase and tensin homolog (PTEN)-induced putative kinase 1 (PINK1) exacerbated kidney injury, indicating that mitophagy plays a protective role in CKD." (PMID 39335620, 2024).
acute lymphoblastic leukemia (2 papers, 2014 to 2021). Leukemia with an acute onset, characterized by the presence of lymphoblasts in the bone marrow and the peripheral blood. "Rotenone, and a combination of mitocans with demonstrated anti-cancer effects (e.g., metformin), may be effective in targeting the PINK1–Parkin pathway of mitophagy in cancer, such as acute lymphoblastic leukemia (ALL)." (PMID 34361072, 2021).
adenomyosis (2 papers, 2023 to 2024). The growth of endometrial tissue inside the muscular wall of the uterine corpus. "Evidence showed that reducing PINK1 levels, a mitophagy regulator, significantly diminishes the invasion potential of endometrial stromal cells (ESCs) in adenomyosis." (PMID 39768424, 2024). "One study specifically investigated the role of mitophagy in adenomyosis, demonstrating an increased expression of PINK1 in the endometrium of patients with adenomyosis and in the uterus of a murine model of the disease." (PMID 39768424, 2024).
alcoholic liver diseases (2 papers, 2022 to 2023). A disorder caused by damage to the liver parenchyma due to alcohol consumption. "Furthermore, PINK1-dependent mitophagy was recently recognized as a novel target for the treatment of alcoholic liver disease and APAP hepatotoxicity." (PMID 36355956, 2022).
Arthritis (2 papers, 2022). Inflammation of a joint. "In conclusion, the present study demonstrated that PINK1 expression was increased in the synovial membranes of RA patients, and that ablation of Pink1 alleviated arthritis in the murine CAIA model." (PMID 35628458, 2022). "In addition, PINK1−/− mice with arthritis exhibited markedly reduced swelling and inflammation relative to wild-type mice with arthritis." (PMID 35628458, 2022). "Furthermore, we induced CAIA in Pink1−/− mice, revealing that arthritis progressed more slowly in Pink−/− mice relative to wild-type CAIA mice." (PMID 35628458, 2022). "In arthritis rat models, resveratrol inhibits the activation of NLRP3 inflammasomes by inducing the PINK1/Parkin-dependent mitophagy." (PMID 35874841, 2022).
astrocytoma (2 papers, 2022 to 2025). "We also demonstrate that PINK1 accumulates at mitochondria in response to activated RhoA in human astrocytoma and rat hepatocyte cell lines, indicating that RhoA regulation of PINK1 accumulation is not a cell-type or species-specific signaling event." (PMID 35760846, 2022).
autoimmune disease (2 papers, 2020 to 2024). A disorder resulting from loss of function or tissue destruction of an organ or multiple organs, arising from humoral or cellular immune responses of the individual to their own tissue constituents. "The PINK1 inhibitors we have discovered were all designed to target other kinases and have primarily been tested in cancer, vascular, and autoimmune diseases." (PMID 38565869, 2024).
behavioral disorders (2 papers, 2022). "Overexpression of PINK1 was able to activate the PINK1-Parkin pathway and rescue IS-induced behavioral disorders." (PMID 36187470, 2022).
Bladder Cancer (2 papers, 2025). "report a novel pathway through which SFXN1 promotes bladder cancer metastasis through the suppression of PTEN-induced kinase 1 (PINK1)-dependent mitophagy." (PMID 41415540, 2025).
COVID-19 (2 papers, 2023 to 2024). A disease caused by infection with severe acute respiratory syndrome coronavirus 2. "In COVID-19, mitophagy is inhibited at an early stage, despite that PINK1 and the Parkin protein are still recruited." (PMID 38974521, 2024). "In the validation dataset, we found consistent metabolic trends in T cells; namely, we found that COVID-19 T cells downregulate key mitophagy genes FUNDC1, PINK1, and CSNK2B and upregulate key Rho GTPase genes RHOA, RHOBTB1, and ARAP3 as well as MTOR compared to HIV-1+ individuals." (PMID 36992700, 2023). "Among the mitobiomarkers associated with the pulmonary version of COVID-19 are PTEN-induced kinase 1 (PINK1), dynamin-1-like protein (DNM1L) and mitofusin-2, which supports the relevance of oxidative stress and aberrations in mitochondrial motility (Chapter 9) in COVID-19 pathogenesis." (PMID 38974521, 2024).
Dengue (2 papers, 2022 to 2023). "The mitophagy flux assays also suggest that dengue inhibits other modes (ubiquitin independent) of mitophagy, in addition to the inhibition of PINK1-PRKN-dependent (ubiquitin dependent) mitophagy." (PMID 40395305, 2023). "Dengue downregulates the expression of PINK1 and Parkin, the two major proteins involved in tagging the damaged mitochondria for elimination through mitophagy." (PMID 36197108, 2022). "Further investigations revealed that dengue derails the well-established pathway of flagging damaged mitochondria for elimination through mitophagy by downregulating the expression of PINK1 and PRKN/parkin, two proteins that play a crucial role in the flagging process." (PMID 40395305, 2023).
diabetic neuropathy (2 papers, 2024). A chronic, pathological complication associated with diabetes mellitus, where nerve damages are incurred due to diabetic microvascular injury involving small blood vessels that supply these nerves, resulting in peripheral and/or autonomic nerve dysfunction. "Painful diabetic neuropathy in the dorsal root ganglion (DRG) induces mitochondrial impairment and sirtuin 3 deficiency, leading to inhibited mitophagy through the FoxO3a‐PINK1‐Parkin pathway, exacerbating allodynia." (PMID 38572816, 2024).
dominant optic atrophy (2 papers, 2014 to 2021). "Finally, PARL is a mitochondrial protease, which cleaves, among others, OPA1 and PINK1, genes responsible for dominant optic atrophy and familial Parkinson’s disease." (PMID 24369379, 2014).
Endotoxemia (2 papers, 2022 to 2023). "Since PINK1-Parkin mitophagy is a major quality control mechanism for mitochondria, we next examined whether myocardial MAMs are also subjected to regulation via the PINK1-Parkin signaling axis during endotoxemia." (PMID 35265609, 2022).
gastric adenocarcinoma (2 papers, 2020 to 2025). "Recent studies underscore how defects in mitochondrial quality control, such as PINK1 insufficiency, can sensitize gastric adenocarcinoma cells to therapies targeting mitochondrial dynamics, linking mitochondrial distress to impaired immune responses." (PMID 41550948, 2025).
hematoma (2 papers, 2021 to 2025). A hematoma is a collection of blood from a vascular structure into an extravascular space. "Decreased PINK1 and mislocated Parkin are found both in the peripheral-hematoma brain tissues of ICH rats and oxygen hemoglobin treated primary neurons." (PMID 35153669, 2021).